IL4 (interleukin 4)
Diseases named in the same sentence as IL4 in open-access papers (continued):
Sharing a sentence is not in itself a finding about the gene and the disease.
allergic rhinitis (141 papers, 2009 to 2026). Inflammation of the nasal mucous membranes caused by an IgE-mediated response to external allergens. "Allergic rhinitis is associated with IL-4 and IL-13 polymorphism, and dual blockade of IL-4 and IL-13 with dupilumab, an IL-4Rα antibody, is required to inhibit type 2 inflammation such as AR." (PMID 38629073, 2024). "According to the cytokine profile in the preseasonal ASIT regimen, the development of allergic rhinitis was predominantly associated with IL-5 and IL-13 production, and bronchial asthma with IL-4, IL-5, IL-13, and TNF-α, which is consistent with other reports." (PMID 36439113, 2022). "The distribution of genotypes of the IL-4 T589C locus polymorphism showed that the rate of the CC genotype and C allele was statistically greater in patients with allergic rhinitis, in contrast to healthy controls." (PMID 35629280, 2022). "The present study aims to evaluate the exact association between IL-4 rs2243250 polymorphism and susceptibility to allergic rhinitis by a meta-analysis." (PMID 33834211, 2021). "The current study aimed to investigate the association of IL-4 polymorphisms with allergic rhinitis." (PMID 32295284, 2020). "As far as we know, this study is the first to evaluate the associations of IL-4 polymorphisms and the risk of allergic rhinitis in Jordan." (PMID 32295284, 2020). "The current study aimed to investigate the association of Interleukin-4 (IL-4) polymorphisms with allergic rhinitis." (PMID 32295284, 2020). "Consistent with other studies, our results in an allergic rhinitis mouse model confirmed that IL-17A deficiency is associated with decreased serum IgE production and IL-4 expression in nasal tissue." (PMID 28046055, 2017). "A study showed that IL-4 gene polymorphism was associated with atopic asthma and allergic rhinitis both of which belong to complex inflammatory disorders, but there were few studies investigating the association between IL-4 gene polymorphism and AD." (PMID 27212784, 2016). "With SHP-1 deficiency, mev mice display an allergic rhinitis-like phenotype, which is largely dependent on Th2 cytokines (IL-4 and IL-13) and eotaxin." (PMID 25090641, 2014). "Studies conducted on allergic rhinitis showed that there is an association of IL-4 with significant increase in IL-13 and TNF α." (PMID 20616938, 2010). "IL-4 -590 C > T polymorphism has a direct association with cancers, and is linked with certain diseases such as atopic asthma & allergic rhinitis and smoking linked cancer; however, many studies report that this polymorphism does not have a significant association with disease incidence." (PMID 35525950, 2022). "Materials and Methods: Our study included 158 patients with allergic rhinitis and 140 healthy controls from Jordan that were genotyped for IL-4 single nucleotide polymorphisms (SNPs) C-589T (rs2243250) and T-2979G (rs2227284) using restriction fragment length polymorphism-polymerase chain reaction." (PMID 32295284, 2020). "A trial in patients with allergic rhinitis found that Spirulina supplementation reduced IL-4 levels." (PMID 41244839, 2025). "For example, monoclonal antibody drugs against IL-4 can be used to treat allergic rhinitis and reduce allergic symptoms by blocking the effect of IL-4." (PMID 40988970, 2025). "A study reported that reflux ethanolic extracts of LE significantly reduced the levels of IL-4 and IL-13 in nasal lavage fluid obtained from murine models of allergic rhinitis." (PMID 41560747, 2025). "Within the context of allergic rhinitis, IL-4–producing CD8 + T cells help maintain ongoing type 2 inflammatory processes." (PMID 39962262, 2025). "Flow cytometry analysis revealed that Rh1 significantly curbed the rise in IL-4+ CD4+ cells in allergic rhinitis mice while elevating IFN-γ+ CD4+ cell proportions, demonstrating restoration of Th1/Th2 immune balance." (PMID 41155644, 2025).
allergic rhinitis (continued). "Ultimately, the ameliorative effect of dictamnine on allergic rhinitis mice was confirmed through nasal symptom score, serum pharmacodynamic indices (immunoglobulin E (IgE), histamine, IL-2, IL-4, IL-6, and TNF-α), and histopathology." (PMID 40520177, 2025). "In a mouse model of allergic rhinitis, treatment with geniposide significantly reduced serum levels of IL-4, IL-5, and IL-17." (PMID 41001345, 2025). "In allergic rhinitis models, Rh1 administration significantly decreased IL-4-positive CD4+ T cells while increasing IFN-γ-positive CD4+ T cells in nasal-associated lymphoid tissue." (PMID 41155644, 2025). "Research shows that Spirulina consumption increases B-group vitamins, particularly B6, and decreases interleukin-4 (IL-4) levels in individuals with allergic rhinitis." (PMID 38655258, 2024). "Splenocytes isolated from the DP-induced allergic rhinitis mouse model exhibited significantly increased IL-4, IL-10, IFN-γ, and TNF-α levels after stimulation with DP." (PMID 39335479, 2024). "Based on a clinical study, the Spirulina extract rectifies the symptoms of allergic rhinitis patients by suppressing IL-4 and Th2 cell differentiation." (PMID 38544605, 2024). "Based on the medical documentation, Spirulina showed significant anti-inflammatory activities by hampering histamine release in mast cells and reducing IL-4 levels (32%) in allergic rhinitis." (PMID 38544605, 2024). "After different administrations, CCR3mAb i.p. group had increased trends in Th1 cytokines (IFN-γ and IL-2) compared to allergic rhinitis mice, with statistical significance; and decreased trends in Th2 cytokines (IL-4, IL-5, and IL-13)." (PMID 38212473, 2024). "Other studies have also found that IL-4, IL-17, and IgE levels are inhibited by infrared-wavelength visible light in mice with allergic rhinitis, and eosinophil infiltration into the nasal mucosa was also significantly decreased." (PMID 36837427, 2023). "There is evidence that T cell-mediated Th2 cytokines including IL-4, IL-5, and IL-13 are elevated in patients with allergic rhinitis, and can regulate eosinophil growth and differentiation." (PMID 35831673, 2023). "In an OVA-induced allergic rhinitis model, oral treatment with naringenin improved nasal symptoms and decreased serum total IgE and Th2 cytokines IL-4 and IL-5 compared with the OVA treated group." (PMID 37998337, 2023). "Mild seasonal pollen allergic rhinitis (AR) treated with intranasal vitamin D adjuvant therapy showed a reduction in AR symptoms (≈40%), serum IL-4, and peripheral blood eosinophils compared to desloratadine citrate disodium (DCD) treatment alone." (PMID 37998337, 2023). "Oral EGCG reduced sneezing episodes, nasal rubbing, serum histamine levels (≈30%), and nasal mucosal expression of inflammatory molecules COX-2, IL-1β, IL-4, and IL-6 in a mouse model of allergic rhinitis." (PMID 37998337, 2023). "Patients with allergic rhinitis taking Arthrospira platensis powder for around 12 weeks showed reduced levels of IL-4 by 32%, which was probably due to the protective effect of microalgae toward allergic rhinitis." (PMID 36984000, 2023). "In a mouse model of allergic rhinitis, gallic acid decreased the IL-4, IL-13, and IL-17 levels in mouse model of allergic rhinitis." (PMID 36235070, 2022). "Th2 cytokines, particularly IL-4, are essential in the pathophysiology of allergic rhinitis and asthma." (PMID 36311721, 2022). "Enhanced IL-4 markedly suppresses the expression of Trek1 via upregulating the expression of the HDAC1 in the nasal mucosa of allergic rhinitis." (PMID 36311721, 2022). "Consuming thyme with an increase in anti-inflammatory cytokine IL-4 and a decrease in IL-5 cytokine control inflammation and improvement in allergic rhinitis symptoms." (PMID 35144653, 2022). "In an allergic rhinitis mouse model, SHEDs inhibited the Th2 immune response by downregulating IL-4, IL-5, and IL-13 levels in spleen lymphocytes and decreasing the production of serum IgE and IgG1." (PMID 35909660, 2022).
allergic rhinitis (continued). "The emerging innovative drugs include mAbs targeting on characteristic pathways of type 2 inflammation, such as those of IgE, the IL-5, and IL-4/IL-13 which are involved in several pathologic condictions including CRSwNP or allergic rhinitis." (PMID 35387050, 2021). "aqueous extract, Syzygium formosum leaf extract, and Wild grape hot-water extract ameliorated allergic rhinitis by inhibiting IL-4." (PMID 34679659, 2021). "Application of A. cepa on the nasal cavity of BALB/c mice with allergic rhinitis revealed remarkable decreases in IgE and inflammatory cytokines IL-4, IL-5, IL-10, and IL-13." (PMID 34552650, 2021). "Acupuncture dramatically reduces IL-4 and IL-10 and upregulates IFN-γ in allergic rhinitis patients, causing a swift of Th1/Th2 balance towards Th1." (PMID 33144870, 2020). "In conclusion, our study reveals that elevated levels of activated and pathogenic eosinophils are a feature of moderate-severe allergic rhinitis and associated with higher production of ECP, EPX, and IL-4 in the peripheral blood." (PMID 32855977, 2020). "Ginsenoside Rd suppressed ovalbumin-induced expression of IgE, IL-4, IL-5, and IL-13 in nasal mucosa and bronchoalveolar lavage fluid and alleviated gut dysbiosis in mice, resulting in the attenuation of allergic rhinitis." (PMID 32326081, 2020). "Employing this knowledge, this study aimed to evaluate alteration in the expression of the genes FOXP3, TGF-β, IL-17, IFN-γ, IL-10, and IL-4 following ARIT protocol in Iranian patients with allergic rhinitis." (PMID 31807241, 2019). "Fu and Yu reported that after six months of aerobic exercise, the serum level of IL-4 significantly decreased in patients with allergic rhinitis." (PMID 32411263, 2019). "In OVA-induced AR rat models, Shenqi relieved the allergic rhinitis symptoms, inhibited the histopathological changes of nasal mucosa, and reduced the levels of IL-4 and IgE." (PMID 28327534, 2017). "The effect of MSCs on the inflammation of allergic rhinitis was evaluated by sneezing, nose rubbing, the pathology of the nasal mucosa, and the expression of interleukin 4, tumour necrosis factor alpha, and immunoglobulin E in the serum of rats." (PMID 28940415, 2017). "Describing the serum cytokine profile especially in seasonal allergic rhinitis, one can note that immune-mediated inflammatory response of the upper respiratory airway mucosa is characterized by a more significant production of IL-4." (PMID 29109963, 2017). "It should be noted that the serum level of IL-4 in patients with allergic rhinitis is 2.1–2.8 times higher than that in the control group." (PMID 29109963, 2017). "Another study showed that β-glucan administration to subjects with seasonal allergic rhinitis resulted in reduced IL-4 and IL-5 levels." (PMID 27390655, 2016). "More recently, the use of anti-IL-4 in combination with AIT for allergic rhinitis was assessed in a double-blind study of 37 patients with seasonal allergic rhinitis." (PMID 26780523, 2016). "Previous reports revealed that several genetic variants of candidate genes, such as ADAM33, IL4, MRPL4, and TNFA, are positively associated with susceptibility to allergic rhinitis." (PMID 26177022, 2015). "Previous study had investigated significant association between IL-4, IFN-gamma promoter methylation and allergic rhinitis patients of Uygur and Han Chinese in Xinjiang." (PMID 26197428, 2015). "Some evidence of a shift in Th1/Th2 balance away from Th2 has been shown in studies of acupuncture treatment of allergic rhinitis in humans, namely, a significant reduction in IL-10 and IL-4 and a significant decrease in gene expression for IL-1R1." (PMID 23476696, 2013). "IL-4 significantly increased in both allergic rhinitis (8.34 fold, P = 0.0424) and mev mice (11.16 fold, P = 0.024) compared with respective controls." (PMID 22509389, 2012).
allergic rhinitis (continued). "IL-4, IL-5, IL-8 and IFN-γ cytokines, especially IL-4 and IL-5, mediate and regulate immune and inflammatory reactions in allergic rhinitis." (PMID 19488556, 2009). "Maternal allergic history may reflect a heritable predisposition to atopy, with several studies identifying polymorphisms in immune-related genes such as IL-4, IL-13, and the filaggrin gene (FLG) that are linked to an increased risk of allergic rhinitis." (PMID 40422270, 2025). "Allergen-specific T helper 2 (Th2) cells and elevated serum IgE are typical manifestations of allergic rhinitis, and the significantly elevated levels of IL-4 and IL-6 also indicate that two cytokines play an important role in the disease process of allergic rhinitis." (PMID 35831673, 2023). "The pathology of allergic rhinitis shows the accumulation and increase of mast cells, dendritic cells, macrophages, etc. in the superficial nasal mucosa, as well as the levels of inflammatory factors such as IL-4, IL-6, IL-8, and IgE were increased." (PMID 35831673, 2023). "Previous studies have provided evidence that individuals with allergic rhinitis or those undergoing allergen immunotherapy exhibit significantly reduced levels of IL-4 compared to untreated individuals, and these levels resemble those observed in non-allergic individuals." (PMID 37386045, 2023). "However, total IgE and IL-4 levels were significantly reduced when the infrared-wavelength visible light used in this study was applied to an allergic rhinitis mouse model." (PMID 36837427, 2023). "All biological functions of IL-4 are mediated by effector IL-4R, including mediating Th1/Th2 imbalance, promoting B cell proliferation and IgE synthesis, which play a crucial role in allergic rhinitis." (PMID 35846137, 2022). "In another in vivo study on balb/c mice, DAP showed anti-inflammatory effects on ovalbumin-induced allergic rhinitis via reducing serum levels of IgE, IL-4, and IFNγ as well as decreased number of mucosal eosinophils and pathological changes in respiratory epithelial." (PMID 35949308, 2022). "When looking into the literature, a decrease in IL-4, IL-5 and IL-13 after acupuncture could be seen in animal experiments, namely in rats suffering from allergic rhinitis." (PMID 35301577, 2022). "To investigate whether LE_R alleviates allergic reactions in an OVA-induced allergic rhinitis mice model, we used ELISA kits to measure the amounts of the T-helper (Th) type 2 cytokines IL-4 and IL-5 in the serum." (PMID 36142314, 2022). "The IL-4/IL-13 axis is involved in the pathogenesis of allergic rhinitis (AR)." (PMID 35372516, 2022). "Additionally, in a double-blinded, randomized, placebo-controlled clinical trial, sulforaphane showed effects in decreasing T2 cytokines such as IL-4, IL-5, and IL-13 in nasal cavity mucus of allergic rhinitis patients." (PMID 34439514, 2021). "Quantitative RT-PCR analysis showed that the expression levels of Il4, a key mediator of Th2 response, and of the Il33 gene, which is necessary for the development of allergic rhinitis, were reduced in the lungs of Mlys-IL-6 KO mice as compared to WT control mice." (PMID 30534125, 2018). "However, in a group of polyposis/non-allergic rhinitis patients, serum VitD was positively correlated with IL-4 and negatively correlated with IFN-γ levels." (PMID 28881831, 2017). "Moreover, therapies that promote immune tolerance, such as allergen immunotherapy, reduce the proportion of IL-4–secreting CD8 + T cells in patients experiencing intermittent allergic rhinitis, suggesting that downregulation of Tc2 responses is integral to its therapeutic mechanism." (PMID 39962262, 2025). "However, IL-4, IL-5 and IL-13 levels may be elevated in the nasal secretion of patients with persistent severe allergic rhinitis." (PMID 30846420, 2020).
allergic rhinitis (continued). "However, in our unpublished study, we have investigated the dose-response relationship of B. breve on a murine allergic rhinitis model, presenting results of decreased IL–4 and OVA-specific IgE levels and increased CD4+CD25+ Tregs in the spleen at a dose of 109CFU.B." (PMID 26445348, 2015). "Because GSEA revealed that the genes upregulated in nasal brushing samples from mite allergic patients and the genes induced by IL-4 and IL-13 were significantly enriched in our dataset, our data support the notion that pathways underlying allergic rhinitis are common regardless of the allergen." (PMID 23950865, 2013). "Treatment of rat models of allergic rhinitis after particulate matter (PM2.5) exposure with RosA (20 mg/kg, i.p.)for 7 days remarkably reduced the levels of IL‐4 and IL‐13, while enhancing IFN‐γ levels in nasal lavage fluid." (PMID 41523289, 2026). "The decrease of allergen‐specific IL‐4+ TFH2 cells and the increase in TFR cells in HDM‐induced allergic rhinitis are related to the improvement of symptoms." (PMID 40765419, 2025). "According to the literature, in experimental mice with allergic rhinitis treated with berberine, serum IgE, GATA-3, IL-4, and IL-13 mRNA levels, as well as tissue eosinophil numbers, were significantly reduced." (PMID 41001345, 2025). "β-glucan also reduced IL4 and IL5 concentrations and increased IL12 concentrations in individuals with allergic rhinitis." (PMID 38655128, 2024). "Studies showed to exposure to PM2.5 worsened symptoms in rats with allergic rhinitis, leading downregulated of IFN-γ and upregulated of IL-4, IL-13, and eosinophils in nasal fluid." (PMID 38961398, 2024). "Another study revealed that adhesion facilitates the differentiation of allergic rhinitis CD4IL4 T cells through ICAM1 and E-Selectin, leading to the production of the anti-inflammatory factor IL4." (PMID 39399526, 2024). "This study was conducted on the bank sample before and after the intervention to measure interleukin-4, interleukin-5, and interferon -γ levels with the ELISA test method in a supernatant taken from the PBMC cell culture from 30 allergic rhinitis patients." (PMID 35144653, 2022). "The expression of IL-4, IL-5, and IL-13 mRNA was significantly higher in mice with OVA-induced allergic rhinitis than in the control group; however, they were significantly lower in mice treated additionally with LE_R or CIC." (PMID 36142314, 2022). "It has been reported that an increase in IL-31 levels was detected in patients with allergic rhinitis and IL-31 induced production of IL-4, IL-5 and IL-13 in PBMC and nasal epithelial cells from patients with allergic rhinitis." (PMID 30647024, 2019). "Supplementation with baicalin in the diet reduced the serum concentrations of IgE, IL-1β, IL-4, IL-6, TNF-α, and histamine in rats with allergic rhinitis, which suggests its potential as a therapeutic agent for allergic rhinitis through inhibition of inflammation mediators." (PMID 41463802, 2025). "Compared to allergic rhinitis mice, CCR3mAb2 and CCR3mAb3 groups had increased trends in Th1 cytokines (IL-2 and IFN-γ), with statistical significance; and decreased trends in Th2 cytokines (IL-4, IL-5, and IL-13)." (PMID 38212473, 2024). "The inhibitory effects of TQ on IL-4 production, OVA-specific IgE, TNF-α and IL-1b gene expression, edema, and eosinophil infiltration in the nasal mucosa were reported in a rat model of allergic rhinitis." (PMID 33859710, 2021). "Firstly, a mouse model of allergic rhinitis was produced by OVA sensitization followed by an OVA challenge, which resulted in nasal symptoms (nose rubbing and sneezing) and increases in IgE/OVA-IgE, as well as IL-4/IL-13 levels in the nasal fluid." (PMID 32899766, 2020). "Furthermore, RG and fRG inhibited IL-4 expression in phorbol 12-myristate-13-acetate/A23187-stimulated RBL-2H3 cells and alleviated ovalbumin-induced allergic rhinitis in mice." (PMID 32326081, 2020).